CDK4 (cyclin dependent kinase 4)
Diseases named in the same sentence as CDK4 in open-access papers (continued):
Sharing a sentence is not in itself a finding about the gene and the disease.
breast cancer (continued). "Targeting cell-cycle proteins has seen some headway in breast cancer treatment, such as using cyclin-dependent kinase (CDK4 and CDK6) inhibitors, but it is still considered in the early days of application." (PMID 39728433, 2024). "A cohort of 31 patients with post-CDK4/6 inhibitor HR+/HER2- advanced breast cancer received CT7001 in combination with fulvestrant, resulting in 3 patients achieving PR with a CBR of 36.0% (9/25)." (PMID 38605321, 2024). "Currently, CDK4/6 inhibitors have been approved for breast cancer and has been shown to suppress RA in animal models." (PMID 38867295, 2024). "In combination with estrogen receptor inhibition, CDK4/6 inhibitors (palbociclib, abemaciclib, ribociclib) prolong survival in breast cancer and have led to a new therapeutic paradigm." (PMID 39139449, 2024). "Our evaluation of the cost-effectiveness of CDK4/6 inhibitors in combination with letrozole as a first-line treatment for HR+/HER2- advanced breast cancer provided valuable insights into the economic and clinical considerations of these therapeutic strategies." (PMID 39114308, 2024). "This study can guide clinicians and decision-makers regarding the best cost-effective use of CDK4/6 inhibitors in the first-line use of HR+/HER2- advanced breast cancer." (PMID 39114308, 2024). "Palbociclib, a cyclin-dependent kinases 4/6 (CDK4/6) inhibitor that induces G1 phase cell cycle arrest, is used in combination with aromatase inhibitors to treat metastatic luminal breast cancer, achieving an overall response rate of 42.1%." (PMID 39723293, 2024). "Next, we evaluated the efficacy of RETi selpercatinib and CDK4/6i palbociclib, alone or combined, in ER+ patient-derived breast cancer organoids (PDO-P48) that exhibited high IC50 towards CDK4/6i, and thus primary resistance to this treatment." (PMID 39931212, 2024). "In this study, we explored the effects of Bruceine D and Narclasine on CDK4 and their role in regulating cell cycle in breast cancer." (PMID 38215156, 2024). "In this study, we aimed to evaluate the efficacy of locoregional RT in advanced breast cancer patients treated with cyclin-dependent kinase 4/6 inhibitors (CDK4/6i) in a first-line setting." (PMID 39065777, 2024). "Cyclin-dependent kinase 4/6 inhibitors are effective as a second-line treatment for hormone receptor-positive human epidermal growth factor 2-negative advanced breast cancer." (PMID 39697231, 2024). "To determine the impact of selective CDK2 inhibition with INX-315 on the transcriptome of CDK4/6i–resistant breast cancer, we treated abemaciclib and abemaciclib/fulvestrant–resistant cells with INX-315 and performed RNA-sequencing." (PMID 38047585, 2024). "The ability of the molecular subtypes to predict benefit from CDK4/6 inhibitors in breast cancer has been evaluated in samples from the PALOMA-216, the NeoPalAna17, and the MONALEESA-2,-3, and -718 studies." (PMID 38992220, 2024). "In breast cancer, simultaneous inhibition of the estrogen receptor and CDK4/6 leads to greater reduction in RB phosphorylation than monotherapy and has led to significant gains in survival." (PMID 39139449, 2024). "Currently, alpelisib is being evaluated in combination with fulvestrant in patients with HR-positive, HER2-negative advanced breast cancer after treatment with CDK4/6 inhibitors and AI in phase III EPIK-B5 trial (NCT05038735)." (PMID 38396649, 2024). "Although small-molecule inhibitors targeting CDK4/6 revolutionized breast cancer therapy and improved hematological malignancy therapies, the drawbacks of their use, such as developing resistance, became apparent." (PMID 39598723, 2024). "It is believed that the inhibition of CDK4 is responsible for the effectiveness of CDK4/6 inhibitors in treating ER+ breast cancer, as CDK4 is the primary kinase in these cancer cells." (PMID 38339303, 2024). "To this end, we measured the viability of several bladder, prostate and breast cancer cells treated with the CDK4/6 inhibitor palbociclib." (PMID 38424044, 2024).
breast cancer (continued). "This is important for breast cancer because the cyclin D/cyclin-dependent kinases 4 and 6 (CDK4/6)–retinoblastoma protein (RB) pathway plays a key role in the proliferation of both normal breast epithelium and breast cancer cells." (PMID 38922546, 2024). "FGFR1 amplification in 12.5% of breast tumors makes ER + breast cancer patients resistant to CDK4/6 inhibitors and endocrine treatments, increasing their likelihood of disease recurrence." (PMID 38831455, 2024). "FDG-PET-CT performed before cyclin-dependent kinase 4/6 inhibitor commencement is a valuable prognostic tool in hormone receptor-positive human epidermal growth factor receptor 2-negative advanced breast cancer." (PMID 39697231, 2024). "Endocrine therapy (ET), with either fulvestrant (Fulv) or aromatase inhibitors (AIs), plus a cyclin-dependent kinase 4/6 inhibitor (CDK4/6i) is the recommended first-line standard of care for patients with HR+/HER2- advanced breast cancer." (PMID 38166684, 2024). "CDK4/6i–resistant breast cancer is a common and difficult clinical challenge, and a critical goal is to identify novel agents that will overcome this resistance by regaining control of the cancer cell cycle." (PMID 38047585, 2024). "A previous study reported that FAT1 loss in breast cancer cells induced YAP activation, promoting CDK4/6 inhibitor resistance." (PMID 38622197, 2024). "A systematic literature search identified phase 3 randomized clinical trials reporting OS of CDK4/6 inhibitors (CDK4/6i) in combination with endocrine therapy in ER-positive/HER2-negative advanced breast cancer." (PMID 38326452, 2024). "The resistance of the CDK4/6 inhibitors in breast cancer patients is characterized by specific and general cell processes that pose efficient barriers against treatments that would help improve the survival of patients with the disease." (PMID 39795972, 2024). "CDK4/6 inhibitors are effective at treating advanced HR+ /HER2- breast cancer, however biomarkers that can predict response are urgently needed." (PMID 38438376, 2024). "For cluster reassignments of breast cancer, the gene with the most interaction-rich feature set was CDK4." (PMID 39333715, 2024). "In many tumors, the expression levels of CDK4/6 are significantly elevated (hematopoietic malignancies, breast cancer, and melanoma), which makes the CDK4/6 inhibitors attractive as therapeutic targets." (PMID 39598723, 2024). "The pragmatic, de-centralized IMPORTANT trial focusing on dose optimization of CDK4/6 -inhibitors in older breast cancer patients is a paradigm of a study design where different mitigating strategies have been adopted." (PMID 38881342, 2024). "Here, we assess the biological changes that occur upon CDK4/6 inhibition in breast cancer cell lines and clinical samples of patients who participated in two neoadjuvant phase II studies of ribociclib or palbociclib in combination with endocrine therapy." (PMID 38992220, 2024). "Consistently, other FDA-approved CDK4/6 inhibitors for breast cancer such as abemaciclib and ribociclib induced senescence and KGA upregulation." (PMID 39695080, 2024). "Palbociclib (Ibrance), ribociclib (Kisqali), and abemaciclib (Verzenio) are three FDA-approved CDK4/6 inhibitors for the treatment of advanced HR+/HER2– breast cancer." (PMID 38327984, 2024). "It prompts further inquiry into the distinctive characteristics of CDK4/6i and their reception and tolerance by different genders and it is important to consider the variety of treatments used for male breast cancer patients." (PMID 38464732, 2024). "Here, we demonstrate a comprehensive analysis of the impact of RR inhibition by DDX in combination with the CDK4/6 inhibitor palbociclib on the cell cycle in parental and palbociclib-resistant ER+ and ER− breast cancer cells." (PMID 38473336, 2024).
breast cancer (continued). "The advancement in treatment outcomes for advanced HR+ breast cancer has been considerably elevated due to the discovery of cyclin-dependent kinase 4/6 inhibitors and their combination effects with endocrine therapy." (PMID 38339303, 2024). "This case provides important insights on primary CDK4/6i plus ET in locally advanced unresectable HR+/HER2- breast cancer and its potential implications in disease management further ahead." (PMID 38601755, 2024). "Potential treatment alternatives include BRAF/MEK inhibitors, which have been useful in the treatment of various cancers like CDKN2A-negative melanoma, and CDK4/6 inhibitors, which have been approved to treat breast cancer." (PMID 38612819, 2024). "CDK4/6 has now gradually become a promising target for HER2‐positive breast cancer, as the cyclin D1/CDK4/6/pRb axis is also a key pathway involved in resistance to HER2‐directed therapy." (PMID 38469548, 2024). "Immunoblot further verified that neratinib effectively downregulated Cyclin D1, CDK4 and EGFR by inhibiting the HER2 pathway, thus enhancing the efficacy of CDK4/6 inhibitor combined with endocrine therapy in HR+/HER2-low breast cancer (P < 0.01)." (PMID 39730704, 2024). "Here, we describe the creation of a novel, potent, and selective inhibitor of CDK2 and characterize its activity in models of CCNE1-amplified cancer and CDK4/6i–resistant luminal breast cancer." (PMID 38047585, 2024). "Of particular importance will be the development of CDK2 + CDK4/6i combinations in the treatment of breast cancer." (PMID 38047585, 2024). "This position paper aims to address specific clinical questions regarding the use of cyclin-dependent kinase 4/6 inhibitors in elderly patients with early or advanced breast cancer." (PMID 38791919, 2024). "NRAS (breast carcinoma and skin melanoma), CDK4 (NSCLC), and ERBB2 (gastric carcinoma and esophageal carcinoma) were identified as the top identified amplification driver genes in different cancer types." (PMID 38195844, 2024). "Advanced ER+ breast cancers are typically treated with hormone therapy and CDK4/6 inhibitors as the standard of care." (PMID 37264081, 2023). "While shortcomings of this study warrant further validation, current evidence recommends maintaining efforts to provide booster immunizations to the most vulnerable breast cancer patients, including those undergoing CDK4/6 inhibition." (PMID 38023235, 2023). "At the clinical level, we verified the roles of LRPPRC in CDK4/6i treatment response by Immunohistochemical (IHC) experiment using samples from breast cancer patients, as breast cancer is the only approved clinical application for CDK4/6i." (PMID 37452037, 2023). "Current evidence recommends maintaining efforts to provide booster immunizations to the most vulnerable cancer patients, including those with advanced breast cancer undergoing CDK4/6 inhibition." (PMID 38023235, 2023). "One such example is the use of immunotherapy in CDK4/6 inhibitor-resistant breast cancer, which holds promise for patients with limited treatment options." (PMID 37511548, 2023). "Patients with advanced HR+/HER2− breast cancer whose disease has progressed on frontline CDK4/6 inhibitors with ET have many options for treatment, but no standard of care exists for the next line of systemic therapy." (PMID 37860199, 2023). "A comparison between immortalized RPE1 and a type of breast cancer cell (MCF7) was performed in order to reveal potential differences in cellular response to CDK4/6 inhibition." (PMID 37894292, 2023). "Given the high activity of camizestrant monotherapy in ER+ PDX models, we investigated camizestrant as the central ET partner to CDK4/6i and other standard-of-care therapies in ER+ breast cancer." (PMID 37725704, 2023).
breast cancer (continued). "The latest studies for the first-line treatment of HR+/HER2− advanced breast cancer (ABC) based on these CDK4/6 inhibitors include the PALOMA series, the MONARCH series, the MONALEESA series, and the DAWNA series, most of which have achieved positive results." (PMID 37444496, 2023). "Despite approvals of other drugs, such as CDK4/6 inhibitors, endocrine resistance remains an important target in metastatic breast cancer and novel treatment options are required." (PMID 36859649, 2023). "Overall, the introduction of CDK4/6i into clinical practice has substantially improved care for patients with metastatic ER+/HER2− breast cancer, yet now is the time to refine and optimize our practice." (PMID 36949066, 2023). "This literature review demonstrates generally limited toxicities with the combination of CDK4/6 inhibitors and palliative radiotherapy to metastatic breast cancer patients." (PMID 37366898, 2023). "According to NCCN Clinical Practice Guidelines 2021 for breast cancer, combined or single use of fulvestrant and/or CDK4/6 inhibitors have been recommended as the first-line or second-line therapeutic regimen for patients with tamoxifen treatment failure." (PMID 36915147, 2023). "In recent years, the FDA has approved several CDK4/6 inhibitors, such as palbociclib, ribociclib and abemaciclib, for the treatment of HR-positive breast cancer patients." (PMID 37686364, 2023). "The use of CDK4/6 inhibition has been effectively employed in the therapy of specific adult breast cancer subtypes." (PMID 36982482, 2023). "In clinics, there are already drugs that specifically inhibit CDK4, such as palbociclib and abemaciclib, for the treatment of breast cancer." (PMID 36769158, 2023). "The treatment landscape for ER+ advanced breast cancer has improved significantly with the addition of the CDK4/6 inhibitors to endocrine therapy as standard treatment." (PMID 36901954, 2023). "In this study, the detailed effectiveness of two of the CDK4/6 inhibiting medications used in the first-line treatment of HR+/HER2- stage IV breast cancer patients in Qatar, palbociclib, and ribociclib, as well as their safety profiles were evaluated." (PMID 38162489, 2023). "The combination of PI3K/AKT/mTOR and CDK4/6 inhibitors has been studied in preclinical models and is still under research in clinical trials in patients with advanced breast cancer (NCT02389842), lung cancer and other cancers (NCT03065062)." (PMID 36792625, 2023). "This clinical trial is assessing the combination of an anti-PD-L1 antibody, avelumab, with a CDK4/6 kinase inhibitor, palbociclib, and endocrine therapy in patients with estrogen receptor-positive breast cancer." (PMID 38067203, 2023). "In the phase III TROPiCS-02 trial, patients with heavily pretreated (median of three prior systemic therapies) ER+/HER2-breast cancer and who received prior CDK4/6 inhibitors were randomized to sacituzumab govitecan or physician’s choice chemotherapy." (PMID 37035239, 2023). "With a better understanding of breast cancer biology and endocrine resistance mechanisms, cyclin-dependent kinase 4/6 inhibitors (CDK4/6i) have been developed, which is clinically effective and tolerable when combined with ET." (PMID 36717797, 2023). "Cyclin-dependent kinase 4/6 (CDK4/6) inhibitors have emerged as an attractive therapeutic strategy in a number of cancers since their approval for treatment in patients with ER+/HER- breast cancer in combination with antiestrogens." (PMID 36765923, 2023). "In contrast to the targeted therapies in HER2-positive breast cancer, there is a relative paucity of data concerning CDK4/6i activity in the brain." (PMID 36902831, 2023).
breast cancer (continued). "More importantly, we found that CPVL promoted drug resistance to CDK4/6 inhibitors by downregulating phosphatase and tensin homolog (PTEN) in vivo and in vitro, indicating that CPVL promotes breast cancer resistance to CDK4/6 inhibitors." (PMID 36825764, 2023). "CDK4/6 inhibitors (CDK4/6i) have improved survival of patients with estrogen receptor-positive (ER+) breast cancer." (PMID 37502925, 2023). "In a randomized, open-label, phase II trial (MonarcHER; NCT02675231), the CDK4/6 inhibitor abemaciclib was assessed in patients with HR+/HER2+ advanced breast cancer (recurrent locally advanced, unresectable, or metastatic disease)." (PMID 37258523, 2023). "Building on the success of CDK4/6 inhibitors in the metastatic setting, further studies have been conducted to assess their efficacy in early breast cancer." (PMID 37511548, 2023). "The standard-of-care in HR+ breast cancer are targeted therapies, such as ER-targeting (e.g. tamoxifen and fulvestrant), aromatase inhibition, or inhibitors of cyclin-dependent kinases 4/6 (CDK4/6), or a combination of these treatments." (PMID 37423299, 2023). "Herein, we present safety and efficacy of CDK4/6i combined with radiation therapy in HR + HER2− breast cancer patients with CNS involvement treated at our institution." (PMID 36902831, 2023). "Palbociclib, a cyclin-dependent kinase 4/6 inhibitor, has been previously studied to treat breast cancer." (PMID 36879299, 2023). "ER+/HER2- advanced breast cancer (ABC) with visceral crisis (VC) or impending VC (IVC) is commonly treated with chemotherapy instead of CDK4/6 inhibitors (CDK4/6i)." (PMID 37584881, 2023). "Palbociclib is a highly selective and orally active CDK4/6 suppressor approved by the FDA for treating ER + breast cancer and is also effective against various cancer." (PMID 36978140, 2023). "For breast cancer, CDK4/6 inhibitors such as ribociclib and palbociclib have been developed as targeted treatments." (PMID 37711177, 2023). "Several clinical studies on inhibitors targeting CDK4 and CDK6 in pRb-positive tumors (breast cancer, melanoma, liposarcoma, and so on) have shown that the cyclin D–CDK4/6–pRb axis has a significant impact on tumor proliferation and transformation." (PMID 36838737, 2023). "Cyclin-dependent kinase 4/6 inhibitors are promising candidates for patients with human epidermal growth factor receptor 2 (HER2)-positive breast cancer." (PMID 37327257, 2023). "Several clinical trials have demonstrated a considerable therapeutic advantage for the use of CDK4/6 inhibitors, like palbociclib, in the treatment of advanced breast cancer that is hormone receptor-positive but HER2-negative." (PMID 37711177, 2023). "In fact, the latest guidelines suggest the use of CDK4/6 inhibitors combined with AIs or fulvestrant as the standard therapy for ER+ advanced breast cancer in both pre- and post-menopausal women." (PMID 37173983, 2023). "The addition of cyclin-dependent kinase 4/6 (CDK4/6) inhibitors to ET in the treatment of advanced-stage breast cancer has boosted responses and survival outcomes over the past few years, especially in the first-line setting." (PMID 37860199, 2023). "The present findings of differentially expressed genes between breast cancer cells that were resistant and sensitive to CDK4/6 inhibitors reveal that CPVL is a potential regulator of drug resistance." (PMID 36825764, 2023). "While CDK4/6 inhibition has proven effective in clinical use in a subset of breast cancers, most patients eventually progress on treatment due to the adaptation and acquired resistance to CDK4/6 inhibition." (PMID 36765923, 2023). "Overall, camizestrant shows strong and broad antitumor activity in ER+ breast cancer as a monotherapy and when combined with CDK4/6i and PI3K/AKT/mTORi." (PMID 37725704, 2023). "CDK4/6i inhibits cell cycle progression by inhibiting the downstream effects of the CDK4/6 complex with cyclin D. Cyclin D amplification is common in HR+ breast cancer." (PMID 36980743, 2023).